POU5F1 (POU class 5 homeobox 1)
Diseases named in the same sentence as POU5F1 in open-access papers (continued):
Sharing a sentence is not in itself a finding about the gene and the disease.
ovarian carcinoma (109 papers, 2010 to 2026). A malignant neoplasm originating from the surface ovarian epithelium. "The IPA knowledge base compared genes with >1.5 fold for those associated with breast and ovarian cancers, and then determined the connections to Oct4/POU5F1." (PMID 29321622, 2018). "In two ovarian cancer cell lines A2780 and HEY cells, reductions of LVRN expression by shRNAs were associated with decreases in POU5F1 expression." (PMID 41024351, 2025). "In contrast, trametinib treatment of PEO4 cells for 10 h significantly promoted the expression of cell stemness regulators SOX2, NANOG, POU5F1 (OCT4), and two ALDH1A homologs associated with elevated chemoresistance and the stem-like phenotype of ovarian cancer cells." (PMID 33803586, 2021). "Increased expression of CSC markers and transcription factors, such as CD44, KIT Proto-Oncogene (KIT, CD117), POU Class 5 Homebox 1 (POU5F1, OCT4), and NANOG, was observed in ovarian cancer cells treated by cisplatin or paclitaxel both in vitro and in vivo." (PMID 35401749, 2022). "Bai S’s study had also proven that EGFL6 promotes the asymmetric division of cancer stem-like cells in ovarian cancer, consistent with this research’s result that EGFL6 could keep the cell stemness by regulating the expression of cancer stem cell associated genes, POU5F1, NANOG, and LIN28." (PMID 33726836, 2021).
embryonal carcinoma (100 papers, 2008 to 2026). A non-seminomatous malignant germ cell tumor characterized by the presence of large germ cells with abundant cytoplasm resembling epithelial cells, geographic necrosis, high mitotic activity, and pseudoglandular and pseudopapillary structures formation. "It regulates stem cell markers such as POU5F1 (OCT4) and SOX2,50,51 associated with GCNIS and embryonal carcinoma." (PMID 39999848, 2025). "Altered histone methylations increase the expression of proto-oncogene POU5F1, which is detectable in embryonal carcinomas and seminomas." (PMID 32235691, 2020). "The same applies to DNAm of the POU5F1-related CpG in embryonal carcinomas and to the “Parthenogenic-Score”." (PMID 25754700, 2015). "In addition, the hypersensitive apoptotic response in embryonal carcinoma cells is determined by the high expression of Oct-4 (octamer-binding transcription factor 4, also known as POU5F1), a key regulator of pluripotency." (PMID 35625709, 2022). "The gain in histone H3K4 dimethylation at the Pou5f1 promoter and associated gene activation we report here following HDAC inhibition and under the combined suppression of KDM1/HDAC is similar to what has been observed in embryonal carcinoma cells." (PMID 20856864, 2010). "That NT2-D1 cells also express NANOG and POU5F1, and can also be induced to differentiate with a subsequent decrease in expression of these factors, supports the hypothesis that these cells represent a true embryonal carcinoma cell line." (PMID 24475288, 2014). "OCT3/4 (POU5F1) is an established diagnostic immunohistochemical marker for specific histological variants of human malignant germ cell tumours (GCTs), including the seminomatous types and the stem cell component of non-seminomas, known as embryonal carcinoma." (PMID 21847120, 2011). "Similar to seminoma and embryonal carcinoma, these cells are uniformly positive for the embryonic stem cell marker OCT4/POU5F1, and these cells are typical of the embryonal carcinoma cells isolated from experimentally induced teratocarcinomas." (PMID 28125050, 2017). "After treatment with ATRA, known to induce differentiation of embryonal carcinoma NT2 cells, LIN28 expression was significantly downregulated, as it happened with pluripotency factors NANOG and POU5F1, with the opposite occurring for PAX6, a marker of differentiation." (PMID 40448114, 2025). "In keeping with a restricted expression of RARγ within primitive cells, the binding sites for RAR/RXR dimers within undifferentiated F9 embryonal carcinoma cells coincided with loci that are targeted by transcription factors that are important to pluripotency (SOX2, NANOG, and POU5f1)." (PMID 37082619, 2023). "Octamer-binding transcription factor 4 (OCT4, also known as POU5F1) is a transcription factor in embryonic stem cells and germ cells that has been found in pluripotent primary testicular germ cell tumors, seminoma, and embryonal carcinoma." (PMID 34513828, 2021). "For example, Utf1, a transcription factor required for the proper differentiation of embryonic carcinoma cells and ESCs40, is enriched after chromosome sorting, while Nanog, Oct4 (Pou5f1) and Klf4, although detected, show no significant enrichment in sorted chromosome samples." (PMID 32807789, 2020). "Current models of GCT differentiation suggest that embryonal carcinoma and seminoma are the undifferentiated types of tumors and that they share many features with normal embryonic stem cells including expression of pluripotency factors such as NANOG, POU5F1, and SOX-2 among others." (PMID 24475288, 2014). "However, unlike the GC-1 cells, embryonal carcinoma cells increased Pou5f1 expression when KDM1 was inhibited by T alone." (PMID 20856864, 2010).
hepatocellular carcinoma (98 papers, 2012 to 2025). A malignant tumor that arises from hepatocytes. "Gankyrin also prevents POU5F1 degradation in hepatocellular carcinoma (HCC) by inhibiting the interaction of POU5F1 with WW domain containing E3 ubiquitin protein ligase (WWP2;." (PMID 31744479, 2019). "In addition, numerous studies have conducted analyses on the expression of POU5F1 mRNA and protein within various tumor types, including bladder cancer, rectal cancer, hepatocellular carcinoma, esophageal squamous cell carcinoma, among others." (PMID 38062041, 2023). "Gankyrin is an oncogene which has been shown to prevent POU5F1 degradation and specifically interact with MAGE-A4 in hepatocellular carcinoma (HCC) cells." (PMID 31744479, 2019).
glioblastoma (92 papers, 2011 to 2026). The most malignant astrocytic tumor (WHO grade IV). "Our analysis identified that OCT4, also known as POU5F1, is a key gene in glioblastoma activated by endogenous viral elements." (PMID 39588508, 2024). "Mitchell and colleagues addressed the critical roles of POU5F1 in WDR5-induced glioblastoma progression." (PMID 37325625, 2023). "In glioblastoma CSCs, VPA downregulates the expression of stemness genes Prominin 1 (PROM1, which encodes CD133), NANOG, and POU Class 5 Homeobox 1 (POU5F1, also known as OCT4) and increases differentiation markers." (PMID 39851500, 2025). "FOXO1 induced the OCT4 (POU class 5 homeobox 1) gene expression in glioblastoma cells." (PMID 36602390, 2023). "These Ly6G+ cells may be an important factor in glioblastoma cell dedifferentiation after radiotherapy, as their expression also correlates with the expression of POU5F1 observed in recurrent GBM patients after radiotherapy." (PMID 30804471, 2019). "On the tissue level, PIWIL1 expression was associated with a stem cell gene signature in non-small cell lung cancer, and expression of the stem cell markers POU5F1 (Oct3/4) and SOX2 and OLIG2 in colorectal cancer and glioblastoma, respectively." (PMID 38303021, 2024). "Both NANOG and POU5F1 are well-known master regulators of pluripotency; specifically, NANOG is implicated in both normal neural stem cell self-renewal and tumorigenesis in glioblastoma multiforme (GBM), while OCT4 functions in the differentiation of neural stem cells into neurons." (PMID 26888867, 2016). "Expression of POU5F1 (OCT3/4), SOX2, and NANOG has been used to identify TSCs in pulmonary neoplasms, oral squamous cell carcinoma, and glioblastoma." (PMID 22870217, 2012).
gastric cancer (80 papers, 2012 to 2025). A primary or metastatic malignant neoplasm involving the stomach. "POU5F1 plays an important role in maintaining the cancer stem cell (CSC) -like properties of gastric cancer (GC) cells." (PMID 38062041, 2023). "POU5F1 is expressed not only in embryonic stem cells and germ cells but also in various types of solid tumor cells, including gastric cancer." (PMID 25046748, 2014). "For instance, POU5F1 promotes gastric cancer (GC) cell proliferation and migration by inhibiting TRAF6 ubiquitination and degradation, thereby activating the NF-κB pathway, and KDM48 stimulates TRAF6-mediated AKT activation and facilitates the progression of rectal cancer." (PMID 40296903, 2025). "Overall, we suggest that LOC441461 modulates gene transcription, inducing the malignancy of gastric cancer by interacting with RELA, IRF1, ESR1, AR, POU5F1, TRIM28, and GATA1." (PMID 35267457, 2022). "The interaction of the transcription factors RELA, IRF1, ESR1, AR, POU5F1, TRIM28, and GATA1 with LOC441461 affected the degree of the malignancy of gastric cancer by modulating gene transcription." (PMID 35267457, 2022). "To predict the relationship between prognosis and the co-expression of OCT4 (POU5F1) and its pseudogenes, we retrieved clinical prognosis data from patients with various types of cancers, including breast, ovarian, lung, and gastric cancers, using the Kaplan-Meier plotter database." (PMID 30287838, 2018).
pancreatic cancer (71 papers, 2011 to 2026). "An experiment has shown that BBR (15 μM) reduces expression levels of SOX2, Nanog and POU5F1 as CSC markers to impair resistance of pancreatic cancer cells to gemcitabine and suppress their progression." (PMID 34769099, 2021). "BBR has been shown to suppress genes associated with stemness such as SOX2, POU5F1, NANOG and NOTCH in the side population of certain pancreatic cancer cell line PANC-1." (PMID 28611316, 2017). "Hence, the authors believed that the stem cell-associated genes (NANOG, POU5F1, and SOX2) may serve as promising markers and that BBR can be considered a potent anticancer agent for the treatment of pancreatic cancers." (PMID 34885950, 2021). "Notably, treating pancreatic cancer cells with Stattic, a STAT3 inhibitor, substantially reversed the upregulation of mRNA expression of tumor stemness markers (NANOG, SOX2 and POU5F1) induced by IL20RB overexpression." (PMID 38098005, 2023).
liver cancer (70 papers, 2013 to 2026). An epithelial or non-epithelial malignant neoplasm that arises from the liver. "POU5F1, a stemness-related transcription factor, was found to promote the liver cancer stem cell phenotype and cancer metastasis and regulate the expression of signature genes of HBV-derived HCC." (PMID 35402224, 2022). "Oct4, which is also known as POU5F1, mediates the stemness of liver cancer via a positive feedback loop with the oncogene c-Jun." (PMID 28137313, 2017).
prostate carcinoma (70 papers, 2011 to 2025). A carcinoma that arises from epithelial cells of the prostate gland. "The SNP located within intron 3 of POU5F1/OCT4 is associated with the recurrence of prostate cancer." (PMID 31013960, 2019). "Cas9-based transcription recording analysis in a human prostate cancer cell line revealed that specific cells express POU5F1 in response to an anticancer drug and sphere formation." (PMID 36564568, 2022). "Reports in the literature have documented the association between LIN28, NANOG, POU5F1, and SOX2 and prostate cancer aggressiveness individually." (PMID 31146720, 2019). "Interestingly, a recent study SPINK1-positive castrate resistant prostate cancer identified POU5F1/OCT4 as part of a gastrointestinal gene signature present in SPINK1-positive prostate cancer and regulated by HNF1A and its target gene HNF4G." (PMID 30074477, 2018). "Overall, our findings demonstrated the significant, reproducible upregulation of a number of genes particularly the stem cell markers NANOG, OCT4/POU5F1 and ALDH1 in prostate cancer holoclones." (PMID 32647229, 2020). "Studies have indicated that H19 might act as an oncogene in prostate cancer by the upregulation of SRY box 2 (SOX2) and POU domain class 5 transcription factor 1 (POU5F1)." (PMID 32878251, 2020). "We postulate that the transition of prostate cancer from adenocarcinoma to non-adenocarcinoma and small cell carcinoma involves activation of scTF genes in the sequence of POU5F1 → LIN28A/SOX2 → NANOG with tumor cells adopting a more de-differentiated state." (PMID 31146720, 2019). "Neither retinoic acid nor cisplatin induced resistance in cervical or prostate cancer cell lines or other germ cell tumor lines in which they failed to alter the expression of NANOG and POU5F1." (PMID 24475288, 2014). "Like 5D3 and SP cells, the different non-luminal-like prostate cancer cell types showed little expression of LIN28, POU5F1, NANOG, SOX2." (PMID 21605402, 2011).
teratoma (69 papers, 2009 to 2025). A non-seminomatous germ cell tumor characterized by the presence of various tissues which correspond to the different germinal layers (endoderm, mesoderm, and ectoderm). "One possible cause of this observed teratoma formation was persistent expression of extrinsic POU5F1 integrated into host DNA." (PMID 35445254, 2022). "The immunohistochemical findings in this case demonstrated positive staining for mesodermal markers, such as desmin and SMA, along with the embryonic stem cell marker OCT4/POU5F1, confirming the diagnosis of a mature teratoma." (PMID 40657604, 2025). "Pou5f1 and Nanog have shown uniform expression across all teratoma cells, both differentiated and undifferentiated." (PMID 33217978, 2020). "We utilized PSCs expressing enhanced green fluorescent protein (EGFP) under the control of the Pou5f1 promoter to study the persistence of potential pluripotent cells during teratoma formation in vivo." (PMID 29312817, 2018). "POU5F1, CREB1, SP1-responsive transcriptome involved in RNA turnover, teratoma formation, and steroid synthesis were found to activated in cluster #4 cancers of the TCGA and GSE99420 cohorts." (PMID 40011822, 2025). "As expected, the Epi-hiPSC teratoma included tissue representative of ectoderm, endoderm, and mesoderm, and POU5F1 expression was almost absent." (PMID 31240131, 2019).
colorectal cancer (67 papers, 2012 to 2026). A primary or metastatic malignant neoplasm that affects the colon or rectum. "POU5F1, a POU class 5 homeobox 1 member, is associated with a poor prognosis, and its expression is significantly increased after chemotherapy in colorectal cancer." (PMID 35267457, 2022). "POU5F1-expressing cells can self-renew and differentiate, contributing to metastasis formation in colorectal cancer (CRC), but it plays an important role in normal pluripotent stem cells." (PMID 33990627, 2021). "These efforts will provide a better understanding of the role of POU5F1 in colorectal cancer." (PMID 37409260, 2023). "Spheroid culture from the HT-29 cell line, a more realistic colorectal cancer in vitro model, shows significantly higher expression of ABCG2, NANOG, SOX2 and POU5F1 compared to 2D cell culture conditions." (PMID 37445716, 2023). "In colorectal carcinoma, TFAP2C enhances the expression of stemness-related factors, such as Nanog homeobox (NANOG), BMI1 proto-oncogene (BMI-1), POU class 5 homeobox 1 (OCT4) and SRY-Box transcription factor (SOX2), and the phenotypes of cancer stem cells." (PMID 37291585, 2023). "In addition, MG cells expressed surface markers of colorectal cancer stem cells (ALDH1A1, CD24, POU5F1, SOX2, and SOX9) to a greater degree compared with non-MG cells." (PMID 31936744, 2020).
cervical carcinoma (66 papers, 2012 to 2025). A carcinoma arising from either the exocervical squamous epithelium or the endocervical glandular epithelium. "Interestingly, consistent with LGR6, TCF7L2, CTNNB1, MYC, and POU5F1 were all related to the poor prognosis of cervical cancer." (PMID 34489551, 2021). "In cervical cancer cells, PIWIL1 overexpression leads to increased expression of stem cell markers POU5F1, NANOG and BMI1, while PIWIL1 downregulation has the opposite effect." (PMID 38303021, 2024). "In contrast, acetylation of POU5F1 mRNA is not observed in human cervical carcinoma (HeLa) cells, indicating that the NAT10 targets different mRNA between normal and cancer cells." (PMID 40288646, 2025).
melanoma (60 papers, 2008 to 2025). A malignant, usually aggressive tumor composed of atypical, neoplastic melanocytes. "Lastly, TCGA dataset revealed that TIPE has a positive relationship with CSCs markers including BMI1, NANOG, NOTCH1, and POU5F1 in melanoma." (PMID 39728923, 2024). "TCGA dataset revealed that TIPE has a positive relationship with CSCs markers, including BMI1, NANOG, NOTCH1, and POU5F1 in melanoma." (PMID 39728923, 2024). "In melanoma cells, POU5F1 expression or transmembrane delivery of Oct-4 protein induced the dedifferentiation and acquisition of typical CSC-like features, including increased expression of KLF4 and NANOG." (PMID 37176108, 2023). "Similarly, Kumar and colleagues showed that POU5F1 was able to promote dedifferentiation of melanoma cells into CSC-like cells." (PMID 29568377, 2018). "Although stemness features have been attributed to melanoma, our evaluation of stemness genes (NANOG, POU5F1, PROM1 and SOX2), revealed a very low expression among the tested cells on 2D culture." (PMID 32230715, 2020). "First, we confirmed a significant induction of stemness NANOG, POU5F1 and PROM1 in the melanoma sphere formation process, in both primary and secondary WT spheres." (PMID 32230715, 2020).
lung adenocarcinoma (55 papers, 2010 to 2025). A carcinoma that arises from the lung and is characterized by the presence of malignant glandular epithelial cells. "The expression level of POU5F1 is associated with the prognosis of CRC patients and with radioresistance of lung adenocarcinoma." (PMID 37636389, 2023). "The clinicopathological correlations with the expressions of both POU5F1 and MMP2 were examined on a TMA containing 55 lung adenocarcinoma specimens to elucidate their associations with the survival of LAC patients." (PMID 24386189, 2013). "We found that the high expression of POU5F1 correlated with an ascending pathologic node (pN) stage for lung adenocarcinoma (P = 0.042)." (PMID 24386189, 2013). "The clinical significance of POU5F1 and matrix metalloproteinase 2 (MMP-2) expressions in the patients with lung adenocarcinoma (LAC) was also investigated." (PMID 24386189, 2013). "Using the criteria described before, high expressions of POU5F1 and MMP-2 were observed in 26 (47.3%) and 39 (70.9%) of 55 lung adenocarcinoma specimens respectively." (PMID 24386189, 2013). "Here, we demonstrated that CSLCs-derived from lung adenocarcinoma (LAC) cells displayed highly invasive and migratory capabilities via expressing high levels of POU5F1 and MMP-2." (PMID 24386189, 2013). "Furthermore, knockdown of POU5F1 impeded tumorigenic and metastatic ability and reversed the EMT process of lung adenocarcinoma." (PMID 26824036, 2015). "The expression of POU5F1 and MMP-2 in 55 cases of lung adenocarcinoma." (PMID 24386189, 2013).